IGF1 (insulin like growth factor 1)
Diseases named in the same sentence as IGF1 in open-access papers (continued):
Sharing a sentence is not in itself a finding about the gene and the disease.
cancer (continued). "In posttherapy HPD tumors, several somatic mutations were observed in known cancer genes that include tumor suppressor genes such as TSC2 and VHL, along with transcriptional upregulation of cancer signaling pathways, which include IGF-1, ERK/MAPK, and PI3K/AKT." (PMID 35399666, 2022). "Researches have shown that IGF-1 level is increased in many site-specific cancers and could activate the signal pathway to promote the development of cancer, including lung, colorectal, breast, and prostate." (PMID 36329881, 2022). "Importantly, IGF1 is a growth factor that stimulates cell proliferation and can promote cancer via inhibition of apoptosis." (PMID 35104377, 2022). "High levels of IGF-1 were reported to relate to the development of cancer, which was hypothesized and observed to increase cancer incidence by promoting cell proliferation." (PMID 36304546, 2022). "The significant KEGG pathways are chemokine signaling pathway (CCL5, CCL18, CCL19, CCL21, CXCL12, CXCL14, CXCL13), ​​NF-kappa B signaling pathway (CCL19, CCL21, CXCL12), intestinal immune network for IgA production (TNFRSF17, CXCL12), pathways in cancer (IGF1, CXCL12)." (PMID 35486660, 2022). "In such an environment increased concentrations of GH/IGF1 might stimulate early stages of cancer cell growth." (PMID 35966052, 2022). "The role of IGF-1 in cancer development is well established." (PMID 35538578, 2022). "However, further long- term observational studies are still needed to unravel the correlation between IGF-1 and cancer." (PMID 35250656, 2022). "A previous study showed that high levels of insulin or a followed-by increase in IGF‐1 may promote cancer growth." (PMID 36106112, 2022). "In addition to this, transforming growth factor beta 1 TGF-β1 and insulin-like growth factor 1 IGF-1, stored in the bone matrix and released upon cancer-induced bone resorption by osteoclasts, are responsible for TRPV1 expression and activity upregulation." (PMID 35163823, 2022). "IGF-1 is a growth factor that plays a critical role in cell proliferation and body growth and is positively correlated with the development of several specific diseases and cancers." (PMID 36552219, 2022). "In this way, preclinical studies of drugs that target IGF1 and/or insulin pathways suggest that modulating this pathway could find applications in cancer." (PMID 35406791, 2022). "Decreased activity of the phosphatidylinositol 3′-kinase (PI3K)/AKT signaling pathway, comprising the extracellular stress protein clusterin and IGF1, under external stimuli is another mechanism thought to be involved in the switching between cancer cell proliferation and dormancy." (PMID 36430404, 2022). "Moreover, high blood sugar itself also enhances the sensitivity of cells to IGF-1, which promotes the occurrence and development of cancer." (PMID 36714554, 2022). "Apart from the improvement in QoL and fatigue, the significant reduction in IGF-1, which can act as an accelerator of tumour development and progression, might be an indicator of the potential benefits of IF for patients with cancer." (PMID 36235868, 2022). "IGF-1 regulates fuel metabolism and is an important regulator of cell growth, proliferation, survival, differentiation and cellular transformation in many types of cancer, including BC12–14." (PMID 35115550, 2022). "The current study further revealed that the positive genetic correlation of height and IGF-1 with cancer remained positively significant with incident cases suggesting that the correlation is related to the commonality within the combined cancers in their gene alteration and gene expression pattern." (PMID 35729236, 2022). "IGF-1 inhibits cell apoptosis and stimulates cell proliferation to promote cancer development." (PMID 35203722, 2022). "A series of drugs targeting IGF-1/IGF1-R in the treatment of cancer are in clinical trials." (PMID 34804946, 2021).
cancer (continued). "IGF‐1, a mitogen for both normal and neoplastic cells, exerts potent antiapoptotic and mitogenic activity in all cells and is expressed in many different types of cancer cells." (PMID 33492754, 2021). "Neither GH nor ULN IGF-1 levels have been associated with cancer or with tumor site in these patients." (PMID 34208601, 2021). "Accordingly, patients affected by Laron syndrome, a disease characterized by congenital deficiency of IGF1, do not develop cancer." (PMID 33673232, 2021). "Given that IGF1 has mitogenic and anti-apoptotic effects, rhIGF1 therapy may stimulate the growth of benign and malignant tumours that pre-exist or develop in patients with SPIGFD." (PMID 33434161, 2021). "Nevertheless, how laminin signaling is coupled with the signals from other niche factors, such as hypoxia and IGF-1, both of which play crucial roles in cancer and stem cell development, remains largely unknown." (PMID 34381769, 2021). "Normal levels of GH and IGF-1 could also promote cancer by increasing spontaneous genomic instability through a RAS or AKT hyperactivation dependent mechanism." (PMID 34572814, 2021). "IGF-1 should be targeted for cancer prevention, and the regulation of its level could be a potential therapeutic point in general and lifestyle medicine." (PMID 34444753, 2021). "Therefore, both the cancer protection mechanism and the radio-resistance mechanism of GH and IGF1 are via their role in regulating cell proliferation and apoptosis." (PMID 34178997, 2021). "For all these four cancer types, multivariable MR adjusted for IGF1 showed consistent results." (PMID 34567085, 2021). "IGF-1 could increase the cell viability of stromal and cancer cells in response to chemotherapy in CRC." (PMID 33768092, 2021). "Exclusive protein restriction was able to induce a reduction in total and free IGF-1 levels, suggesting that reduced protein intake could represent an important component of anti-cancer dietary interventions." (PMID 34684639, 2021). "Interestingly, high levels of IGF-1/ IGF1-R were also reported to be associated with poor OS and cancer aggressiveness in RCC." (PMID 33882870, 2021). "Insulin-like growth factor 1 (IGF1) may be secreted by stromal cells to regulate cancer cell growth through binding their receptors on the cancer cell." (PMID 34676217, 2021). "According to some studies, high levels of IGF1 in circulation and an elevated IGF1/IGFBP3 ratio disrupt growth hormone (GH)/IGF1 balance, which might be a sign of cancer risk." (PMID 34680577, 2021). "IGF-1 in the human serum signaling axis is required for cell transformation and promotes cancers." (PMID 34452353, 2021). "IGF‐1 was shown to decrease programmed cell death and increase cancer cell differentiation." (PMID 34528373, 2021). "IGF1 also plays a central role in cancer development, stimulates mitosis, and inhibits apoptosis." (PMID 34508103, 2021). "More importantly, IGF-1 and IGF-1R expression were correlated with tumor mutation burden (TMB), microsatellite instability (MSI), mismatch repair (MMR), and DNA methyltransferase (DNMT) of different types of cancers." (PMID 34804946, 2021). "Insulin acts as a cancer-promoting agent that could promote the bioavailability of insulin-like growth factor (IGF)-1 by the inhibition of IGF-binding protein production 35,36." (PMID 34024765, 2021). "IGF-1 (insulin-like growth factor 1) belongs to the gene family responsible for the regulation of cell proliferation, differentiation, apoptosis and metastasis of cancers." (PMID 34925436, 2021). "Interestingly, anti-IGF1R therapies (cixutumumab) or radiotherapy can promote an immune-suppressive microenvironment due to IGF2- or CAF-dependent IGF1 release from cancer cells." (PMID 34065119, 2021). "Recently, it has been found that IGF-1 signaling pathway may play an important role in various cancer types, and the key proteins in IGF-1 signaling pathway may become an effective point in the treatment of human malignancies." (PMID 34233689, 2021).
cancer (continued). "In addition, CAFs can promote irradiated cancer cell recovery and tumor relapse after RT by producing insulin-like growth factor-1/2 (IGF-1/2), C-X-C motif chemokine ligand 12 (CXCL12), and β-hydroxybutyrate." (PMID 34646829, 2021). "The role of the IGF1 signaling axis on cancer etiology has been well established." (PMID 34220714, 2021). "However, as concomitant anti‐IGF1/IGFR inhibitor development in adult cancers was stopped for futility the development was also stopped in ES, without further research for efficacy biomarkers resistance mechanisms to the drugs." (PMID 33452711, 2021). "However, the roles of GH and IGF1 in promoting cell proliferation and inhibiting cell apoptosis simultaneously increase the difficulty in cancer radiotherapy due to their contributions to radio-resistance." (PMID 34178997, 2021). "In multivariable MR, BMR was positively associated with cancer after adjusting for IGF1 overall and in women but not in men." (PMID 34567085, 2021). "Similarly, the overexpression of the metalloproteinases ADAM17 and ADAM28, which specifically act on IGFBP3, favors cancer cells proliferation by enhancing IGF1 bioavailability." (PMID 33673232, 2021). "When higher‐order interaction effects are not accounted for, higher IGF‐1 appeared to be more consistently associated with cancer risk across ages." (PMID 34363732, 2021). "Ionizing radiation may lead to changes in the serum levels of cancer-related hormones and proteins in cancer-free women, including IGF1." (PMID 34178997, 2021). "Additionally, when IGF-1 function was blocked by miR-28-5p, the expressions of cancer stemness-related genes SOX2, OCT4, and NANOG were repressed." (PMID 33669204, 2021). "Increased expression of IGF-1 and its cellular receptors are present in cancer tumours." (PMID 34324486, 2021). "Analysis of the whole kinome (779 kinases) siRNA screen, showed an overexpression of 6-phosphofructo-2-kinase fructose-2,6-biphosphatase 3 (PFKFB3), a positive regulator of glycolysis in adipocytes and cancer cells, as a positive regulator of insulin/IGF-1 pathway." (PMID 34208601, 2021). "Long-term CR is reported to reduce IGF-1 serum levels in rodents by ~30–40%, protecting them against several types of cancers, while treatments with GH or IGF-1 can reverse this protective effect mediated by CR, confirming the important role of these factors in cancer pathogenesis." (PMID 34572814, 2021). "In certain cancer cells, binding of IGF-1 to IGF-1R could activate some signaling pathway and then promote oncogenic effect." (PMID 34175839, 2021). "Signaling pathways activated by IGF1/IGF1R respond to radiotherapy in several types of cancer." (PMID 34178997, 2021). "In addition, IL-6 treatment induced IGF-1 secretion and IGF-1R expression in NANOG/OCT4-HCC cell lines in a dose-dependent manner, suggesting crosstalk between IL-6/STAT3 signaling and IGF/IGF-1R signaling in HCC cancer stem cells." (PMID 33669204, 2021). "In addition, studies have indicated that cancer cell proliferation increases in a dose-dependent manner with increasing concentrations of IGF-1." (PMID 34485159, 2021). "Based on the roles of GH and IGF1 signaling pathways on anti-apoptotic and mitogenic, the abnormally high expression of GH and IGF1 in cancer cells may lead to their resistance to radiotherapy." (PMID 34178997, 2021). "Moreover, in cancer research, it was suggested that miR-152 is involved in the IGF-1-mediated miR-152/PKM2/β-catenin regulatory circuit that regulates cell proliferation and angiogenesis." (PMID 33291523, 2020).
cancer (continued). "Nuclear IGF-1R traffics from the plasma membrane and the levels of IGF-1R nuclear translocation are proportional to ligand-induced kinase activation, because its translocation in cancer cells can be inhibited by xentuzumab, an IGF-1/2 neutralizing antibody, or by inhibition of IGF-1R endocytosis." (PMID 33584548, 2020). "Diminished IGF1 levels in LS patients lead to relaxation of expression and/or activation of pro-survival, anti-apoptotic signaling pathways, with important consequences in terms of cancer avoidance." (PMID 33182502, 2020). "IGF1 has been reported to regulate tumor progression in multiple cancers." (PMID 32851683, 2020). "As the phosphoinositide 3-kinase (PI3K) pathway may trigger the transduction responses mediated by the IGF-1/IGF-1R system in cancer cells, we asked whether the PI3K/AKT signaling is involved in the activation of FAK in TNBC cells." (PMID 32325700, 2020). "IGF-1 increased mitochondrial biogenesis in cancer cell lines." (PMID 32802505, 2020). "Data on circulating IGF‐1 levels in relation to other cancers are limited and inconclusive." (PMID 32717139, 2020). "For instance, lower levels of IGF-1 were associated with increased risk for cardiovascular disease, while high IGF-1 levels were related to increased risk for cancer; although the findings were not consistent in all studies." (PMID 32492897, 2020). "Thus, cancer cell viability was dependent on IGF-1 stimulation of mitochondrial biogenesis and mitophagy." (PMID 32802505, 2020). "Moreover, pancreatic CAFs produced more insulin-like growth factor 1 (IGF1), and cancer cells increased the expression of IGF1 receptor (IGF1R) in response to hypoxia." (PMID 32503591, 2020). "In other human cancers, an increase in expression of the two other mRNA isoforms, IGF1Eb and IGF1Ec, as well as respective IGF1 pro-peptides might also be observed." (PMID 32977489, 2020). "Moreover, we will discuss some genetic alterations that cause GH and IGF-1 insensitivity and the arguments in favor and against the influence of GH/IGF-1 on longevity and cancer in the light of the papers on these issues that so far appear in the literature." (PMID 32092880, 2020). "We recently reported that IGF-1 induces a transcriptional programme for mitochondrial biogenesis, while also inducing expression of the mitophagy receptor BCL2/adenovirus E1B 19 kDa protein-interacting protein 3 (BNIP3), suggesting that IGF-1 has a key mitochondria-protective role in cancer cells." (PMID 31936236, 2020). "A plausible explanation of the differential protective effect of fasting against chemotherapy is the attenuation of the Ras/MAPK and PI3K/Akt pathways downstream of decreased IGF-1 in normal cells contrary to the oncogene-driven constitutive activation of these pathways in cancer cells." (PMID 33271979, 2020). "Consequently, a high concentration of IGF-1 suppresses apoptosis and induces cell cycle progression, angiogenesis, and metastatic activity in various cancers." (PMID 31942181, 2020). "In addition to the competitive antagonism of estrogen, HD-TOR has been suggested to suppress cancer growth through the dose-dependent inhibition of the insulin-like growth factor 1 (IGF-1)/MAPK/ERK signaling pathway." (PMID 32099680, 2020). "Besides, clinical evidence also suggests that elevated insulin and IGF-1 levels favor the progression of a variety of cancers." (PMID 32512898, 2020). "Interestingly, VIM, besides being a key regulator of cell adhesion and cell–cell interactions, has a well-known role in the EMT process in many types of cancer, while IGFBP6 is particularly implicated in the IGF1-mediated EMT." (PMID 32878319, 2020).
cancer (continued). "Simultaneously, cancer cells activate osteoblasts by releasing parathyroid hormone-like protein (PTHrP), Wnt-1, insulin-like growth factor (IGF)-1, and BMPs and/or using Jag1/Notch pathway, and activated osteoblasts further enhance osteoclast generation and activation by releasing RANKL." (PMID 33050237, 2020). "Finally, in PC patients, several clinical studies confirmed the correlation between poorer survival and increased IGF-1 serum concentrations, as well as low blood level of IGF-binding proteins (IGFBPs), supporting the role of IGF-1 signaling in this cancer." (PMID 32659999, 2020). "It has been speculated that a high protein animal-based diet may accelerate IGF-1 secretion, which may promote cancer progression." (PMID 33374289, 2020). "While a decline in IGF-1 in the periphery may be beneficial to avert cancer progression, diminished central IGF-1 signaling may mediate, in part, age-related cognitive dysfunction and cognitive pathologies potentially by decreasing mitochondrial function." (PMID 31732912, 2020). "In vitro, insulin is a growth stimulator that is more potent than IGF-1 in some cancer cells." (PMID 32156062, 2020). "This view is further supported by the fact that many previous studies trying to correlate systemic bloodstream levels of IGF1 and cancer have remained inconclusive, while, on the contrary, high IGF-II blood levels have been often reported to be associated with a variety of solid cancers." (PMID 33266015, 2020). "However, similarly to the association between IGF-1 and CVD, recent findings suggest that both low and high levels of IGF-1 are associated with cancer mortality." (PMID 33261185, 2020). "The knowledge of the basic functional effects of IGF1 gene AS could contribute to the discovery of new molecular mechanisms of carcinogenesis and, consequently, to the use of that knowledge in anti-cancer therapeutic approaches." (PMID 32977489, 2020). "IGF1/IGF1R signaling is therefore an attractive therapeutic target for cancer." (PMID 32033461, 2020). "IGF1 has been acknowledged to be involved in diverse pathological processes, including cancer." (PMID 33298061, 2020). "One of the lowest levels of Ec peptide expression might indicate the role of other factors (apart from cancer type and hormone receptor status) in a given pattern of IGF1 mRNA expression in BC." (PMID 32977489, 2020). "Higher levels of circulating insulin may promote cancer development by affecting insulin-like growth factor-binding proteins and by increasing IGF1 bioactivity, which has proliferative, angiogenic, antiapoptotic, and estrogen-stimulating properties." (PMID 31906594, 2020). "Controversy over the role(s) of IGF signaling in cancer and whether its inhibition would be of benefit, still persist and extend to IGF1’s role in longevity and central nervous system function." (PMID 32226608, 2020). "In addition, increased serum levels of IGF-1 have been observed in cancers of the lung, colon, prostate and breast." (PMID 32545325, 2020). "Therefore, GHR inhibition appears to be a safer and validated point of intervention to suppress cancer growth and especially drug resistance, as well as in reducing circulating IGF-1 levels and improving insulin sensitivity." (PMID 33291663, 2020). "This indicates that lowering the plasma insulin levels or blocking its activity could provide an additional target in cancer therapy and may be effective in combination with IGF1 inhibition." (PMID 33260481, 2020). "Furthermore, CAFs can promote irradiated cancer cell recovery and tumor relapse after RT by producing insulin-like growth factor-1/2 (IGF-1/2), C-X-C motif chemokine ligand 12 (CXCL12), and β-hydroxybutyrate." (PMID 33050580, 2020). "Using a dietary intervention to downregulate the IGF-1 pathway could represent an ideal strategy to employ in clinical practice since the downregulation of this pathway is known to decrease cancer progression and metastases." (PMID 32211051, 2020).